CD5 (CD5 molecule)
Diseases named in the same sentence as CD5 in open-access papers (continued):
Sharing a sentence is not in itself a finding about the gene and the disease.
helminth infection (2 papers, 2018 to 2024). "In summary, our results expand the pathogen binding properties of CD5 and CD6 and suggest their therapeutic potential against helminth infections." (PMID 30500820, 2018). "In humans, its role is less understood; B1 cells are not defined by CD5 expression; however, B cells expressing this marker are more abundant in natural states of tolerance or helminth infection." (PMID 39312581, 2024). "PECs harbor CD5 and/or CD6 expressing immune cells involved in helminth infection protection." (PMID 30500820, 2018).
hemophagocytic lymphohistiocytosis (2 papers, 2020 to 2026). "This article reports the diagnosis and treatment of a rare case of a patient with ANKL and concurrent CD5(+)CD10(-) monoclonal B-cell lymphocytosis and hemophagocytic lymphohistiocytosis (HLH), and the relevant literature was reviewed." (PMID 42161665, 2026).
Hemophagocytosis (2 papers, 2024). Phagocytosis by macrophages of erythrocytes, leukocytes, platelets, and their precursors in bone marrow and other tissues. "Bone marrow aspirate showed hypocellularity and hemophagocytosis, and the bone marrow biopsy confirmed a bone marrow localization of CD3+, CD8+, CD4−, CD5+, and CD20− peripheral T lymphoma." (PMID 38892108, 2024).
HIV-1 infection (2 papers, 2014 to 2020). The type species of lentivirus and the etiologic agent of acquired immunodeficiency syndrome (AIDS). "Random forest analysis was performed to pin-point proteins discriminating between groups; five proteins (STAMBP, CD5, TFG-α, TRANCE, AXIN1) were the strongest prediction factors for treated HIV-1 infection." (PMID 32906648, 2020).
Hodgkins lymphoma (2 papers, 2013 to 2022). A heterogeneous group of malignant lymphoid neoplasms of B-cell origin characterized histologically by the presence of Hodgkin and Reed-Sternberg (HRS) cells in the vast majority of cases. "A review of classic Hodgkin's lymphoma showed that approximately 5% (12 of 259 cases) expressed at least one T-cell marker in the following order: CD2, CD4, CD3, CD5, and CD8." (PMID 23738160, 2013).
immunotoxicity (2 papers, 2021 to 2022). "We hypothesized that CD5+ ILBs may be sensitive to AHR-mediated immunotoxicity." (PMID 33936048, 2021). "Additionally, antibody blockade of PD-1 or its ligands restored IgM secretion in TCDD-treated CD5+ B cells suggesting, for the first time, a direct role for PD-1 in TCDD-mediated immunotoxicity." (PMID 35558082, 2022).
infectious mononucleosis (2 papers, 2015 to 2023). A condition characterized by an increase in mononuclear white blood cells and swollen lymph nodes, which is usually caused by infection with the Epstein-Barr virus. "Different from T cells in infectious mononucleosis, these T cells demonstrated more evident downregulation of CD5 antigen in addition to loss of CD7 and bright HLA-DR expression by immunophenotyping." (PMID 26451265, 2015). "Toga proposed that clonal expansion of CD8+ T cells with CD5 downregulation as characteristic immunophenotypic features of EBV associated HLH as a tool to distinguish patients with infectious mononucleosis since no such population was identified in patients with infectious mononucleosis." (PMID 26451265, 2015).
intestinal inflammation (2 papers, 2012 to 2016). "B cells expressing high levels of CD1d and CD5 have been linked to the regulation of chronic intestinal inflammation, experimental arthritis, and T cell-mediated inflammation through IL-10 secretion." (PMID 23071588, 2012).
leishmaniasis (2 papers, 2021 to 2023). Infectious disease that is transmitted through the bite of hematophagous female phlebotomine sand flies. "In leishmaniasis, IL-10 secreted by CD5+CD1d+ B cells polarized the Th cell response toward the Th2 phenotype, leading to susceptibility to infection with the parasite in BALB/c mice." (PMID 33750870, 2021). "Among these 14 pathways, four major pathways were enriched: SNARE interactions involved in the vesicular transport (BET1 and STX6), leishmaniasis (FCGR1A, CYBB, and FOS), hematopoietic cell lineages (FCGR1A, ITGA3, MME, and CD5) and Fanconi anemia pathway (SLX4, ATR, and TELO2)." (PMID 37601105, 2023).
liver disease (2 papers, 2012 to 2024). "IgM and IgD molecules were further detected on CD19+B220+CD5+CD27+ NSw MBCs and CD19+B220+CD138+ PBs in murine liver disease." (PMID 39611128, 2024).
lung squamous cell carcinoma (2 papers, 2022 to 2023). "CD5 and CD117 are generally used as diagnostic markers for TSCC; however, lung squamous cell carcinoma (LSCC) occasionally expresses CD5 (0–15%) or CD117 (6.2–20%)." (PMID 36088333, 2022).
mediastinal tumor (2 papers, 2015 to 2024). "Thus, CD5 or CD117/CD5 coexpression in a upper mediastinal tumor is a strong argument for a thymic primary and argues against SqCC of the lung." (PMID 26643918, 2015). "TC is a very rare mediastinal tumor characterized by morphological features of obvious malignant biological behavior and with peculiar immunophenotypic expression of CD5 and CD117 (c-kit), unlike conventional carcinomas of other anatomical sites." (PMID 38966177, 2024).
monoclonal gammopathy (2 papers, 2021 to 2025). A condition characterized by the abnormal presence of monoclonal immunoglobulins in the blood or urine. "Median values (1st–3rd quartile) were 1.47 (1.31–1.73) in mature B lymphocytes, 1.59 (1.40–1.96) in CD5+ B lymphocytes, 1.47 (1.20–1.67) in plasma cells, and 1.53 (1.08–2.45) in CD56+ plasma cells, indicating a balanced light chain production and ruling out monoclonal gammopathy." (PMID 40940803, 2025).
mycosis fungoides (2 papers, 2022 to 2025). Classical mycosis fungoides is the most common type of mycosis fungoides (MF), a form of cutaneous T-cell lymphoma, and is characterized by slow progression from patches to more infiltrated plaques and eventually to tumors. "This study aimed to determine whether immunohistochemical loss of T-cell markers CD2, CD3, CD5, and CD7 in patients with early-stage mycosis fungoides is associated with overall survival and progression-free survival." (PMID 40981343, 2025). "This study explored the prognostic significance of immunohistochemical loss of T-cell antigens—specifically CD2, CD3, CD5, and CD7—in patients diagnosed with early-stage mycosis fungoides (MF)." (PMID 40981343, 2025).
nephritis (2 papers, 2014 to 2022). Inflammation of renal tissue. "The ancestral Ala471 CD5 allele confers lymphocyte hyper-responsiveness to TCR/CD3 cross-linking and is associated with nephritis in SLE patients." (PMID 25402503, 2014). "Allelic combinations conformed by the rs2241002-rs2229177 CD5 SNPs in overall SLE patients, SLE patients stratified according to nephritis status (N+; N−), and controls." (PMID 25402503, 2014). "Similarly, the adoptive transfer of Bregs (CD1d + CD5 + B cells) into CD19 − / − NZB/W F1 mice restored splenic Tregs and delayed the development of nephritis." (PMID 36510250, 2022).
parasitemia (2 papers, 2021 to 2022). "The population of IL-10 producing B220+CD5+CD1d+ cells was found to be directly correlated with the increase of parasitemia in both lethal and non-lethal strains of Plasmodium at early stage of infection." (PMID 35625397, 2022).
Pleural effusion (2 papers, 2013 to 2020). The presence of an excessive amount of fluid in the pleural cavity. "The FL‐SJC cells expressed CD19, CD10, CD22, HLA‐DR, CD38, Lambda and CD20, but did not express CD23, CD5 and Kappa, which was similar to that of the original FL cell from pleural effusion." (PMID 32459397, 2020).
preeclampsia (2 papers, 2020 to 2021). Preeclampsia is a hypertensive disorder of pregnancy that is characterized by new-onset hypertension with proteinuria presenting after 20 weeks of gestation, and depending on mild or severe forms may initially present with severe headache, visual disturbances, and hyperreflexia. "What is more, the frequency of CD19+CD5+ cells in preeclampsia cases is higher than that of the second and third trimester of healthy pregnancy cases and is correlated with the production of autoantibodies." (PMID 34298914, 2021). "In preeclampsia, we have showed that CD5+CD19+ B cells might serve as indicators for this pregnancy-related disorder, at least partly by the release of autoantibodies connected with disorder-specific symptoms." (PMID 32265904, 2020).
sarcoma (2 papers, 2023). A usually aggressive malignant neoplasm of the soft tissue or bone. "In our CLL cohort, CD5+CD19+CD27+ cells represented the discriminant phenotypic features of IL10+vs- and TGFβ1+vs- subsets, which also resembled CD19+CD81+CD27+CD25+PD-L1hi tumor evoked Bregs producing both IL10 and TGFβ1 in sarcomas." (PMID 36973425, 2023).
T cell neoplasms (2 papers, 2022 to 2025). "A panel of differentiation markers CD20, CD23 and CD5 were used to confirm neoplasms of B cells while T cell neoplasms were identified with CD3 and CD5." (PMID 36405938, 2022).
Thymic adenocarcinoma (2 papers, 2021 to 2025). "Thymic adenocarcinoma often positive for CD5 and/or CD117, which are negative in adenocarcinomas of other sites." (PMID 33847622, 2021).
thyroid carcinoma (2 papers, 2022 to 2024). "Furthermore, morular areas of cribriform morular thyroid carcinoma often lack TTF-1 expression but have CDX2, CD5, and CK5." (PMID 38835742, 2024).
abscess (1 paper, 2024). An inflammatory process characterized by the accumulation of pus within a newly formed tissue cavity which is the result of a bacterial, fungal, or parasitic infection or the presence of a foreign body. "Since these steers had an immune response occurring at the abscess site, the increase in circulating mature B cells, CD5, and MHCIIhi cells compared to steers without the immune response, which may result in an increased response time to antigens." (PMID 38764468, 2024).
acquired angioedema (1 paper, 2025). Acquired angioedema (AAE) is characterized by the occurrence of transitory and recurrent subcutaneous and/or submucosal edemas resulting in swelling and/or abdominal pain due to an acquired C1 inhibitor (C1-INH) deficiency. "Given her history of CD5-negative low-grade B-cell lymphoproliferative disorder, a diagnosis of acquired angioedema was made following multidisciplinary review, and treatment with icatibant was initiated." (PMID 41245944, 2025).
acute leukemia (1 paper, 2025). A clonal (malignant) hematopoietic disorder with an acute onset, affecting the bone marrow and the peripheral blood. "Flow cytometry of bone marrow biopsy revealed an immature (blast) cell population expressing CD5, CD34, and CD38, highly suggestive of acute leukemia, particularly AML, given the co-expression of CD13 and CD33 found in peripheral blood." (PMID 40978971, 2025).
adenoma (1 paper, 2025). A neoplasm arising from the epithelium. "Other ILC subsets, such as CD4(+) ILC1, CD5(+) mature ILC1, immature ILCs, and LT-ILC155, may also play important roles in FAP-related tumorigenesis and should be explored in future studies to further clarify the immune landscape of FAP adenomas." (PMID 40280932, 2025).
Adenopathy (1 paper, 2015). "We report an unusual case of an advanced stage of CD5 negative MCL with a blastoid variant with a massive bone marrow (BM) necrosis as an initial presenting feature, with no adenopathy or hepatosplenomegaly." (PMID 26347832, 2015).
adenosquamous cell carcinoma (1 paper, 2022). "Five patients diagnosed with adenosquamous cell carcinoma by histopathological examination, seven who underwent hepatopancreatoduodenectomy, and one with a serious postoperative complication (CD5) were excluded." (PMID 35655260, 2022).
anaphylaxis (1 paper, 2016). An acute hypersensitivity reaction that occurs from exposure to an allergen. "We have previously demonstrated the presence of IL-10-producing CD5+ B cells and suggested their potential role in regulating cow’s milk casein allergy in humans and IgE-mediated anaphylaxis in mice." (PMID 26785945, 2016).
anaplastic plasmacytoma (1 paper, 2009). "The tumor cells were lambda light chain restricted and positive for CD45, weakly positive for CD79a and negative for CD20, CD30, CD10, CD5, BCl-2, Bcl-6, Pax5 and S100, and consistent with anaplastic plasmacytoma." (PMID 19495405, 2009).
ascariasis (1 paper, 2024). An infection that is caused by the roundworm Ascaris lumbricoides, many cases of which remain asymptomatic. "Ascariasis was associated with higher frequencies of CD5+ B cells." (PMID 39312581, 2024).
aseptic meningitis (1 paper, 2019). Inflammation of the membranes surrounding the brain and spinal cord without a bacterial pathogen. "We report a rare case of aberrant CD5-negative MCL presenting with aseptic meningitis." (PMID 31234647, 2019).
autoimmune hemolytic anemia (1 paper, 2022). Autoimmune hemolytic anemia (AIHA) is an autoimmune disorder in which various types of auto-antibodies are directed against red blood cells causing their survival to be shortened and resulting in hemolytic anemia. "CLL is also characterized by distinct immunophenotypes, presenting deficiencies such as autoimmune hemolytic anemia (AIHA), immune thrombocytopenia (ITP), and immune neutropenia, in addition to the presence of CD5+, CD19+, CD20DIM, CD23+ cells." (PMID 36230534, 2022).
B cell deficiency (1 paper, 2021). A broad classification of disorders where circulating numbers of B lymphocytes are decreased or ineffective. "A previous study demonstrated that B1 (CD19+CD5+) and B2 lymphocytes (CD19+CD5–) are negatively associated with the progression of CKD but positively correlated with the survival of elderly CKD patients, suggesting B cell deficiency could be a prognostic factor of CKD progression." (PMID 33718407, 2021).
basal cell carcinoma (1 paper, 2023). A carcinoma involving the basal cells. "We present a case of CD5+ PCDLBCL-LT presenting as a 6 mm pink-bluish nodule on the mid-left thigh, which was concerning for basal cell carcinoma." (PMID 37754668, 2023).
basaloid carcinoma (1 paper, 2017). A malignant epithelial neoplasm characterized by the presence of neoplastic cells with hyperchromatic nuclei, small amount of cytoplasm, and peripheral nuclear palisading. "Basaloid carcinoma usually expresses p63 and p40, rarely CD5 and CK5/6, but is negative for neuroendocrine markers like synaptophysin and chromogranin." (PMID 28602157, 2017).
blood disease (1 paper, 2023). A disease that occurs in the blood. "In this model, the leukemic CD19+CD5+ cells are detected in the spleen after 3 to 5 months and the blood disease only appears after more than one year of age (13 to 18 months)." (PMID 38136362, 2023).
bronchiolitis (1 paper, 2020). Inflammation of the bronchioles characterized by swelling of the bronchioles and mucus accumulation. "CD5+ nBregs have been associated with bronchiolitis severity in human newborns." (PMID 32751234, 2020).
bronchitis (1 paper, 2018). An acute or chronic inflammatory process affecting the bronchi. "Infant CD2 suffered from pharyngitis; CD3 suffered from an upper respiratory tract infection; CD5 suffered from otitis; CD6 and CD8 suffered from an upper respiratory tract infection and also from otitis, and control C5 suffered from bronchitis." (PMID 29458413, 2018).
Candidemia (1 paper, 2025). A form of invasive candidiasis where species of CANDIDA are present in the blood. "The highest upregulated expressions in isolated candidemia included CXCL6, LAP-TGF beta-1, CXCL1, CXCL11, and CD5, while in candidemia with bacterial co-infection, CXCL11, CD40, uPA, CXCL1, CXCL10, and IL-18 were the most abundantly upregulated." (PMID 41229429, 2025).
cervical cancer (1 paper, 2019). A primary or metastatic malignant neoplasm involving the cervix. "The percentage of CD19+CD5+CD1d+ Breg cells and the level of IL-10 of patients with cervical cancer or CIN were significantly higher than those in the control group (P < 0.05)." (PMID 31316301, 2019). "In order to understand the role of Bregs in patients with cervical cancer, we analyzed CD1d+CD5+CD19+ Breg cells and the level of IL-10." (PMID 31316301, 2019). "The percentage of CD19+CD5+CD1d+ Breg lymphocytes in the PBMC of healthy controls, CIN patients, and cervical cancer patients was measured by flow cytometry." (PMID 31316301, 2019).
Chronic colitis (1 paper, 2016). A chronic inflammatory disease of the large intestine (colon, cecum and rectum). "In the present study, we investigated the involvement of colonic CD5+ B cells and compared them with CD5- B cells using model mice with acute or chronic colitis." (PMID 26727001, 2016).
chronic rhinosinusitis (1 paper, 2017). Chronic form of sinusitis. "We observed that CD5+ ILCs were not present in inflamed nasal polyps (data not shown) of patients suffering chronic rhinosinusitis with nasal polyps in which ILC2 accumulate, suggesting that immature CD5+ ILCs fully differentiate into mature CD5− ILCs under inflammatory conditions." (PMID 28912776, 2017).
co-infection (1 paper, 2021). "In addition, the qPCR analysis showed the chemokines ccl4, ccr6, ccr9, and cd5 were significantly down-regulated during lice infection alone vs pre-infection, and comparable with that of co-infection." (PMID 35046944, 2021).
cold agglutinin disease (1 paper, 2021). Cold agglutinin disease is a type of autoimmune hemolytic anemia defined by the presence of cold autoantibodies (autoantibodies which are active at temperatures below 30B0C). "It should be noted that cold agglutinin disease (CAD), sustained by monoclonal cold reactive IgM autoantibodies, is almost invariably associated with a CD5+CD20+ B cell clone, often hardly distinguishable from other NHL." (PMID 33810369, 2021).
Dystonia (1 paper, 2025). An abnormally increased muscular tone that causes fixed abnormal postures. "Baclofen acts as a GABA receptor agonist, and its dystonia-relieving effects may be mediated through inhibition of the spinal reflex pathway; however, its association with CD5 suggests a potential immunomodulatory mechanism." (PMID 40988181, 2025).
endothelial dysfunction (1 paper, 2024). In vascular diseases, endothelial dysfunction is a systemic pathological state of the endothelium (the inner lining of blood vessels) and can be broadly defined as an imbalance between vasodilating and vasoconstricting substances produced by (or acting on) the endothelium. "Additionally, CHD-related endothelial dysfunction may affect immune cell behavior, including CD5 expression." (PMID 39465855, 2024).
enteritis (1 paper, 2022). Inflammation of the small intestine. "Most notably, DSS treatment caused severe enteritis only in the absence of CD5." (PMID 35720357, 2022).
eosinophilia (1 paper, 2025). "Bone marrow flow cytometry demonstrated eosinophilia and 3% atypical T-cells with an immunophenotype of CD3−, CD4+, CD2+, CD5+, CD7−, CD8−." (PMID 41488087, 2025).
food allergy (1 paper, 2016). Gastrointestinal disturbances, skin eruptions, or shock due to allergic reactions to allergens in food. "Overall, our results suggest that IL-10-producing CD5+ B cells are associated with development of oral tolerance for foods and may provide new insight on therapeutic approaches for treatment of food allergies." (PMID 26785945, 2016). "In addition, the population and percentage of IL-10-producing CD5+ B cells were significantly elevated by CIA and more so in OT mice, suggesting again that IL-10-producing CD5+ B cells in MLN are possibly associated with the regulation of food allergy in mice." (PMID 26785945, 2016).